NXPE4 (neurexophilin and PC-esterase domain family member 4)
Synonyms: C11orf33; FAM55D; FLJ20127
Tractability: Antibody: UniProt places it where antibodies can reach, with high confidence; UniProt predicts a signal peptide or a membrane-spanning region; its Gene Ontology location is reachable by antibodies, with medium confidence.
Gene: Protein-coding gene on chromosome 11 (114,570,591 to 114,598,282, reverse strand). Ensembl gene ENSG00000137634.
Subcellular location: Secreted
Gene Ontology:
Cellular component: extracellular exosome; extracellular region
Genetic constraint (gnomAD): Loss-of-function variants: 37 observed, 30.98 expected, observed/expected ratio (o/e) 1.19, 90% interval 0.92 to 1.57. The upper end of that interval is the gene's LOEUF score, 1.57, which puts it in group 6 of 6, group 1 being the genes least tolerant of losing a copy. Missense variants: 639 observed, 604.14 expected, observed/expected ratio (o/e) 1.06, 90% interval 0.99 to 1.13. Synonymous variants: 229 observed, 222.36 expected, observed/expected ratio (o/e) 1.03, 90% interval 0.92 to 1.15.
Homologues: Orthologues: chimpanzee NXPE4 (99% identical), macaque NXPE1 (95% identical), dog NXPE4 (79% identical), mouse Nxpe4 (73% identical), guinea pig NXPE4 (72% identical), rat Nxpe4 (71% identical). Paralogues in human: NXPE1 (68% identical), NXPE2 (63% identical), NXPE3 (29% identical).
Diseases named in the same sentence as NXPE4 in open-access papers:
NXPE4 is named in the same sentence as 12 diseases in open-access papers, as found by Europe PMC text mining. Sharing a sentence is not in itself a finding about the gene and the disease. The quoted sentences say what the papers report.
colorectal cancer (2 papers, 2022). A primary or metastatic malignant neoplasm that affects the colon or rectum. "The high expression of NXPE4 also had a significantly improved prognosis of colorectal cancer regarding patients' overall survival." (PMID 34931221, 2022).
ulcerative colitis (2 papers, 2020 to 2022). An inflammatory bowel disease involving the mucosal surface of the large intestine and rectum. "Neurexophilin and PC-Esterase Domain Family, Member 4 (NXPE4), which has biased expression in colon, is potentially associated with ulcerative colitis, as is P21 activated protein kinase 1 (PAK1)." (PMID 33308304, 2020).
Colon cancer (1 paper, 2023). "Colon cancer patients with decreased Nxpe4 expression were found to have high mortality, and Cygb-deficient mice with increased colon tumors also exhibited decreased Nxpe4 expression." (PMID 38139000, 2023).
Constipation (1 paper, 2024). Infrequent or difficult evacuation of feces. "In the present study, the expression levels of the EDN1 and NXPE4 genes were upregulated 2.06- and 2.00-fold, respectively, during C3 deficiency-induced constipation." (PMID 39273477, 2024).
tumor (2 papers, 2023 to 2025). "Survival analysis indicates that low NXPE4 expression is associated with poorer prognosis, highlighting its potential role in tumor suppression." (PMID 39895793, 2025). "Results showed increased levels of CDKN2A and PLCB4 in tumor tissues, whereas NXPE4 expression was higher in normal tissues." (PMID 39895793, 2025). "In contrast, NXPE4 expression is generally lower in CRC tissues and cells compared to normal tissues, suggesting that NXPE4 may be important for maintaining normal cell functions and inhibiting tumor progression." (PMID 39895793, 2025). "We examined the expression levels of CDKN2A, NXPE4, and PLCB4 in normal and tumor tissues using data from the TCGA database." (PMID 39895793, 2025). "In summary, PLCB4 and NXPE4 exhibit distinct expression patterns and functions across various CRC tissue and cell types, reflecting their complex and dual roles in tumor biology." (PMID 39895793, 2025).
NXPE4 also shares sentences with these, for which no sentence is quoted: carcinoma (1 paper); colitis (1); colon tumors (1); hyperprolinemia type 2 (1); infection (1); mastitis (1); viral infection (1).